CD74 (CD74 molecule)
Diseases named in the same sentence as CD74 in open-access papers (continued):
Sharing a sentence is not in itself a finding about the gene and the disease.
lung carcinoma (continued). "Consequently, the high expression of CD74 on neutrophils presents a promising therapeutic target for augmenting lung cancer immunotherapy." (PMID 41254689, 2025). "Whether the role of CD74 in intrinsic resistance to osimertinib is related to the multiple CD74 fusion proteins reported in lung cancer remains to be investigated." (PMID 39001552, 2024). "The identified lncRNAs and CD74 mRNA may serve as potential prognostic markers or therapeutic targets to improve the overall survival (OS) of patients with lung cancer." (PMID 39001552, 2024). "We found four proteins associated with cancer that in observational long time-to-diagnosis analyses, and cis-pQTL and exGS analyses; CD74 and TNFRSF1B were associated with NHL, and ADAM8 and SFTPA2, were associated with risk of leukaemia and lung cancer, respectively." (PMID 38750076, 2024). "In addition, CD74 can form oncogenic fusion genes with NRG1 to promote the progression of lung cancer cell." (PMID 37745301, 2023). "CD74 protein was also strongly expressed in many lung cancer tissues." (PMID 30943926, 2019). "More recently, association of CD74 and MIF co-expression in lung cancers, and the identification of MIF by label-free proteomic approaches as one of many promising biomarkers in NSCLC, provides additional evidence of the importance of MIF in lung cancer development and progression." (PMID 23522304, 2013). "In summary, various neutrophil subtypes and their expressed molecules—such as CD74, defensins, PDL1, MPO, NE, and NETs—hold promise as predictive biomarkers for immunotherapy in lung cancer." (PMID 41254689, 2025). "In lung cancer specifically, several NRG1 fusion partners, including CD74, ATP1B1, SLC3A2, SDC4, RBPMS, and WRN, have been identified." (PMID 40730881, 2025). "Our CRC patient study as well as patient studies of lung cancer and colon carcinomatosis indicate that MIF/CD74 co-expression corresponds to an even worse prognosis." (PMID 33542244, 2021). "As a high-affinity membrane receptor, CD74 is involved in multiple signaling pathways mediated by macrophage migration inhibitor (MIF), including promoting the Warburg effect by activating the NF-κB/HIF-1α pathway in lung cancer." (PMID 36358600, 2022). "The most recently identified CD74 fusion protein was CD74-NRG2α in a 70-year-old female, never-smoker, stage IIIA acinar adenocarcinoma lung cancer patient." (PMID 37958963, 2023).
multiple myeloma (27 papers, 2013 to 2025). "Milatuzumab, a humanized mouse monoclonal to LL1 (anti-CD74) antibody, was evaluated in phase I clinical trial in multiple myeloma." (PMID 38685050, 2024). "A monoclonal antibody targeting CD74 (milatuzumab) has received US FDA approval for multiple myeloma, a malignancy of B cells where MIF–CD74 survival pathways are highly active." (PMID 38178143, 2024). "Our findings show that CD74 is strongly expressed in myeloma cells compared to healthy cells and has a role in the oncogenic process of cell proliferation and survival." (PMID 30079703, 2019). "CD74 modulates B cell, T cell and dendritic cell responses and milatuzumab, an anti-CD74 antibody, has orphan drug status for the treatment of multiple myeloma and chronic lymphocytic leukemia." (PMID 29924850, 2018). "The anti-CD74 antibody hLL1 milatuzumab, has received orphan drug status for the hematologic malignancies multiple myeloma and chronic lymphocytic lymphoma." (PMID 29924850, 2018). "CD74 expression was also observed in many cancers, including hematological malignancies (multiple myeloma), as well as solid tumors, such as gastric cancer, kidney, small cell lung cancer, epithelial carcinoma of the thyroid, and sarcomas." (PMID 23572149, 2013). "Overexpression of CD74 was reported in various cancers (stomach, kidney, lung and multiple myeloma), suggesting that it can serve as a prognostic factor, with higher CD74 values indicating tumor progression." (PMID 23572149, 2013). "It was found that CD74 is expressed in lymphoma, multiple myeloma, leukemia, and thymic cancers." (PMID 39056676, 2024). "Thus, addition of CD74-targeting antibody milatuzumab to current chemotherapy regimens can offer new therapeutic interventions, as also suggested in prior studies in multiple myeloma models." (PMID 25304249, 2014). "However, metastatic multiple myeloma cell types are known to internally transport and subsequently metabolize approximately 8 × 106 molecules of anti-CD74 monoclonal antibody per day." (PMID 25844392, 2014). "Thus, CD74 plays a role in diverse diseases, either as a promoter of disease (e.g. glomerulonephritis), as a protective molecule (e.g. liver fibrosis) or as a therapeutic target that allows selective destruction of a tumor cell population (e.g. myeloma cells)." (PMID 29924850, 2018). "MIF interacts with CD74 and CXCR4 on myeloma cells to promote their proliferation, survival, and immune evasion, and also supports the inflammatory environment in the bone marrow to promote tumor progression and immune suppression." (PMID 40406148, 2025). "Therapeutic monoclonal antibodies targeting MIF (imalumab) and its canonical receptor CD74 (milatuzumab) have been developed, with milatuzumab achieving orphan drug designation from the FDA for the treatment of multiple myeloma." (PMID 41122966, 2025). "APP signaling regulates the interaction between myeloma cells and bone marrow stroma through CD74 and CXCR4 receptors, affects the adhesion of myeloma cells to the bone marrow microenvironment, and leads to immune evasion by altering immune cell responses." (PMID 40406148, 2025). "Milatuzumab, the first anti-CD74 monoclonal antibody approved by the FDA for clinical practice, is effective at treating aggressive B cell malignancies such as multiple myeloma, especially in combination with rituximab." (PMID 36353222, 2022). "An antibody targeting CD74 (Milatuzumab) underwent clinical trials (NCT00504972) and has been granted Orphan Drug Designation by the FDA for the treatment of CLL and multiple myeloma." (PMID 33324425, 2020). "The phase I/II clinical study of anti-CD74 antibody-doxorubicin conjugate, (IMMU-110) was developed for multiple myeloma." (PMID 30781490, 2019). "In addition, screening of multiple myeloma surface antigens has identified other promising targets, including CD28 (Tp44), CD48 (BLAST), CD74 (CLIP), CD138 (SDC1), CD229 (SLAMF3), CD319 (SLAMF7), CCR10 (GPR2), TAC1 (NPK), TXNDC11, SLC1A5 (AAAT)." (PMID 41369346, 2025).
multiple myeloma (continued). "Overexpression of CD74, a type II transmembrane glycoprotein involved in MHC class II antigen presentation, has been reported in many B-cell non-Hodgkin lymphomas (NHLs) and in multiple myeloma (MM)." (PMID 36634212, 2023). "Targets expressed in normal bone marrow plasma cells can be divided in those in which expression in myeloma cells remains stable in later stages in longitudinal samples (i.e., CD38, CS1, BCMA, FCRH5, CD74, CD79B), and those for which expression is stage-dependently lost (e.g., CD19, CD22, BAFF-R)." (PMID 38035078, 2023). "The approval of milatuzumab, a humanized CD74-targeting antibody in human multiple myeloma and non-Hodgkin lymphoma, and ongoing development of antibodies that target MIF provide candidates to test for therapeutic effects on PNs." (PMID 36134665, 2022). "CD74 expression is rather limited in normal human tissues, but it was found to be overexpressed in more than 85% of non-Hodgkin lymphoma (NHL), chronic lymphocytic leukemia (CLL) and a majority of multiple myeloma (MM) cells." (PMID 25304249, 2014). "Notably, across these lines we detected almost all of the major immunotherapy targets in myeloma, as well as canonical flow cytometry markers for plasma cells: BCMA, CD138/SDC1, CD38, CD56, SLAMF7/CS-1, CD46, Integrin-b7 (ITGB7), CD74/HLA-DR, TACI, CD48/SLAMF2, and LY9/CD229." (PMID 35840578, 2022). "Milatuzumab, the first anti-CD74 antibody that has entered into clinical tests, is currently being studied for the treatment of non Hodgkin lymphomas, chronic lymphocytic leukemia, and multiple myeloma and could be potentially tested in MIF/CD74 positive CRC-pc." (PMID 28114961, 2017). "CD74 expression is limited to HLA class II-positive cells in normal tissues, but its overexpression has been noted in NHL and multiple myeloma (MM)." (PMID 36634212, 2023). "ADCs targeting BCMA, CD38, CD46, CD56, CD74, CD138 are not discussed here since this special issue contains another article devoted to ADCs in multiple myeloma, and these targets are mainly explored in this disease setting." (PMID 36654819, 2022).
autoimmune disease (25 papers, 2012 to 2026). A disorder resulting from loss of function or tissue destruction of an organ or multiple organs, arising from humoral or cellular immune responses of the individual to their own tissue constituents. "Of the six DE genes between AAb and ND donors, the most interesting one in terms of autoimmune diseases is CD74, also known as HLA Class II antigen associated invariant chain, which is part of the class II major histocompatibility complex (MHC)." (PMID 33753784, 2021). "Dysregulation of CD74 expression and function has been associated with several autoimmune diseases including rheumatoid arthritis, systemic lupus erythematosus, inflammatory bowel disease, and autoimmune thyroid diseases, highlighting its importance in the immune system." (PMID 41439980, 2025). "Besides their importance in normal and malignant cell settings, MIF and CD74 are implicated in the etiology of numerous autoimmune diseases, including autoimmune liver disease, kidney disease, and multiple sclerosis." (PMID 38730725, 2024). "In a mouse model of experimental ischaemia-reperfusion injury, renal tubular injury was more severe in MIF, MIF-2 and CD74 knockout mice than in wild-type control mice, and the autoimmune disease systemic lupus erythematosus (SLE) can cause renal inflammation known as lupus nephritis." (PMID 36445632, 2023). "Mechanistically, we found that OVX significantly reduced thymic Cd74 (the MHC class II invariant chain) expression, a central hub gene associated with autoimmune diseases." (PMID 41596668, 2026). "The anti-CD74 monoclonal antibody milatuzumab has shown preclinical activity in B-cell malignancies and early clinical exploration in hematologic cancers and autoimmune disease." (PMID 41439980, 2025). "MIF can regulate CD74 activity, leading to homeostatic imbalances such as inflammation, tumors, and autoimmune diseases." (PMID 40867844, 2025). "Dysregulation of CD74 cleavage and its interaction with proteases has been linked to diverse pathological conditions, including cancer and autoimmune diseases, where aberrant protease activity disrupts CD74 function and promotes disease progression." (PMID 41439980, 2025). "The membrane protein CD74 is the high-affinity receptor of MIF, and MIF can regulate the activity of CD74, causing homeostatic disorders such as inflammation, tumor and autoimmune diseases." (PMID 38625586, 2024). "The well-documented involvement of MIF and CD74 in the balance of the immune system and the pathogenesis of autoimmune diseases suggests they are promising candidates for future research as biomarkers of irAE development following ICB treatment." (PMID 38730725, 2024). "Taken together, these findings show that PSMB9, CD74, and HLA-F all play important roles in presenting antigens and triggering autoimmune diseases." (PMID 37153570, 2023). "As a proinflammatory mediator secreted by numerous immune cells, MIF promotes inflammation and autoimmune diseases mainly by binding with the receptor CD74 and co-receptor CD44, CXCR4, or CXCR2." (PMID 36046240, 2022). "Currently, Milatuzumab, an anti-CD74 monoclonal antibody, has been tested in numerous phase I-II clinical trials in a variety of tumors as well as autoimmune diseases." (PMID 36712241, 2022). "The GSEA and GSVA analyses showed that the positively co-expressed genes of CD74 were enriched in immune responses and autoimmune diseases." (PMID 34540893, 2021). "CD74 also play an important role in of MHC class II antigen presentation in autoimmune diseases, such as systemic lupus erythematosus." (PMID 34007409, 2021). "Given that thymic epithelial cell (TEC) Cd74 expression critically regulates autoimmune diseases, decreased thymic Cd74 expression may occur in TECs of OVX mice and thereby enhance autoimmune susceptibility." (PMID 41596668, 2026). "CD74 has the potential to be a therapeutic target in cancer and autoimmune disease." (PMID 35651784, 2022).
autoimmune disease (continued). "Further studies, including in vivo data that also take into account the complex interaction with other immune and non-immune cells expressing CD74 and targeted by milatuzumab, are needed to fully delineate the potential of anti-CD74 therapy in autoimmune diseases." (PMID 22404985, 2012). "Notably, in addition to the known autoantibodies associated with autoimmune diseases with a higher incidence of CIP, some studies reported a nearly 1.34-fold increase in anti-CD74 plasma level in patients with CIP, while CD74 was related to interstitial pneumonitis." (PMID 36703957, 2022). "In addition to autoimmune disease, CD74 plays a role in renal tubular epithelial cells." (PMID 34007409, 2021). "Notably, deletion of Cd74 substantially reduces peptide diversity of MHC class II molecules, impairs the elimination of autoreactive T cells in the thymus, and causes defects in Treg development by downregulating Foxp3, ultimately promoting autoimmune diseases." (PMID 41596668, 2026). "MIF is known to be involved in the progression of inflammatory and autoimmune diseases and interacts with various receptors, including CXCR2, CXCR4, and CD74 (Bucala 2013, Morrison and Kleemann 2015)." (PMID 37740953, 2023). "Deletion of CD74 leads to reduced peptide diversity of MHC class II molecules on the surface of medullary thymic epithelial cells (mTECs), allowing partial escape of high-affinity autoreactive T cells and, therefore, inducing autoimmune diseases." (PMID 41596668, 2026).
COVID-19 (25 papers, 2021 to 2025). A disease caused by infection with severe acute respiratory syndrome coronavirus 2. "Although the association between HLA class II and COVID-19 has been uncovered in many previous studies, our study revealed that the molecular interplay between HLA class II and CIITA/CD74 is a key marker underlying the severity of COVID-19." (PMID 40163554, 2025). "Taken together, we demonstrate that the disease progression of COVID-19 is associated with a substantial increase in the expression of CD74 on the CM, EM and E subpopulations of total convCD4+ and CD8+ T cells." (PMID 37946732, 2023). "In order to determine the association between the expression of CD74 and its co-receptors with the differentiation status of convCD4+ T cells from COVID-19 patients, flow cytometric analyses were performed." (PMID 37946732, 2023). "Specifically, we sought to investigate the expression levels of CD74 and D-DT in COVID-19 patients and to examine their potential association with disease severity." (PMID 37568438, 2023). "A mild disease course did also not lead to a significant increase in the frequencies of CD74+ CD8+ T cells, whereas severe COVID-19 was associated with increased percentages of CD74+ CD8+ T cells (mean: healthy 11.6%, mild 12.4% severe 21.7%)." (PMID 37946732, 2023). "Our results suggest that not only HLA class II but also its molecular interplay with CIITA/CD74 may be a key marker for uncovering the mechanism underlying COVID-19 severity." (PMID 40163554, 2025). "The proposed computational network biology strategy revealed the molecular interplay between HLA class II and the identified COVID-19 markers CIITA/CD74 as a COVID-19 severity sepcific marker in the Japanese population." (PMID 40163554, 2025). "Our analysis suggests the gene network between HLA class II, CIITA, and CD74 as a COVID-19 severity specific molecular marker." (PMID 40163554, 2025). "In particular, the identified network comprising HLA class II, CIITA, and CD74 likely played a role in COVID-19 severity, i.e., it was demonstrated that the antiviral activities of CIITA and CD74 protect against coronaviruses." (PMID 40163554, 2025). "Our findings from computational network biology analysis suggest that suppression and activation of the molecular interplay between HLA class II, CIITA, and CD74 provide crucial clues to uncover the mechanisms of COVID-19 severity." (PMID 40163554, 2025). "Lastly, in a cohort of 30 COVID-19 patients, CD74 surface expression was found to be significantly upregulated on CD4+ and CD8+ T cells in patients with severe compared to patients with only mild disease course." (PMID 38992165, 2024). "We confirm high CD74 surface expression in T cells under disease conditions in critically ill COVID-19 patients potentially linking dysregulated CD74 to disease severity." (PMID 38992165, 2024). "ConvCD4+ T cells as well as CD8+ T cells from COVID-19 patients or healthy controls were stratified into CD74+ and CD74- cells and the percentage of T cells expressing intracellular Ki-67, a surrogate marker for proliferation, was detected." (PMID 37946732, 2023). "This expression can make T lymphocytes more susceptible to MIF signaling and to CD74-dependent activation, since also the signaling coreceptor molecules CXCR2 and CXCR4 were enhanced on T cells in COVID-19 patients." (PMID 37946732, 2023). "A significantly higher proportion of CD4+ and CD8+ T cells from COVID-19 patients expressed CD74 on the cell surface compared to healthy controls." (PMID 37946732, 2023). "Analyzing absolute numbers of T cell subpopulations confirmed that COVID-19 patients have higher numbers of CD74+ effector T cells in the blood, which was especially true for effector CD8+ T cells (Supplement 3B)." (PMID 37946732, 2023). "In conclusion, our study sheds light on the involvement of CD74 and D-DT in COVID-19, with potential implications for disease severity and treatment." (PMID 37568438, 2023).